IL10 (interleukin 10)
Diseases named in the same sentence as IL10 in open-access papers (continued):
Sharing a sentence is not in itself a finding about the gene and the disease.
infection (continued). "scSIV-LMP1 infection resulted in a significant increase in IL-1β, IL-6, IL-8, IL-10, IL-12p70 and TNF, while scSIV-LMP1-CD40 infection resulted in increase in IL-1β, IL-6, IL-8, IL-10 and TNF at various time points." (PMID 21592361, 2011). "Previous studies showed that IL-10 promoted replication of C. burnetii in human monocytes and C. burnetii established a more robust infection in IL-10-overexpressing transgenic mice owing to the macrophages failing to kill the bacteria." (PMID 21888659, 2011). "IL-10 concentration was significantly increased (p < 0.01) in Lc-S and Lc-S-Lc groups compared to S group, for 7 and 10 days post-infection." (PMID 21813005, 2011). "Infection of newborn mice with GBS WT strain NEM316 resulted in a rapid increase of serum IL-10 concentration." (PMID 22114550, 2011). "IL-10 was expressed in macrophage, dendritic cells and NK cells in the mouse spleen, specifically in response to infection with S. Typhimurium expressing Vi polysaccharide." (PMID 21829346, 2011). "In SIV-infected rhesus macaques, IL-10 production in LNs is already detected at day 7 and increases further by day 28 post-infection." (PMID 21852945, 2011). "In general, the resolution of infection requires a coordinated response in which initial pro-inflammatory mechanisms clear the parasite and then are down-modulated by IL-10 before pathology occurs." (PMID 21917128, 2011). "Typical of the response to infection with helminth parasites, spleen cells from the infected mice produced significantly more IL-4 and IL-10 when challenged with the T cell-mitogen, concanavalin A, than splenocytes from CFA-only-treated or naïve mice." (PMID 21584243, 2011). "Immunization of RhCMV- infected animals was performed since disruption of the IL-10 signaling pathway has been proposed as a therapeutic intervention to alter the course of persistent pathogen infections (see Discussion)." (PMID 22132227, 2011). "Our results showed that P3 infection enhanced the releases of IL-10 and CCL2 of DCs but suppressed the production of IFN-α and TNF-α." (PMID 21269456, 2011). "Our results using the conditional deletion of the IL-10 receptor a chain, which is unique to IL-10, firmly establish that effector T cells are able to respond to IL-10 directly in vivo during infection." (PMID 21829368, 2011). "IFNγ was not detectable in either1x or 4x mice, while only limited amounts of IL-10 were detected, supporting thethesis that multiple infections induce lymphoid hypo-responsiveness." (PMID 21445234, 2011). "Upon stimulation with parasites, IL-10 was detected at low levels in lymph node cells isolated from mice inoculated with either isolate three and five weeks post-infection." (PMID 21390155, 2011). "This raised the possibility of viral persistence or secondary infection resulted from immunosuppression mediated synergistically by IL-6 and IL-10." (PMID 22174866, 2011). "We detected both CD25- and CD25+ Tr1 cells induced by VP1 as early as 1.5 years of HCV infection whereas the majority of IL-10+ cells beyond 2.5 years of infection were predominantly CD25+." (PMID 21801418, 2011). "TLR7-/- MDSCs, when compared to B6, not only show increased recruitment to the site of infection and secrete increased amounts of Th1 inhibiting IL-10 in vivo, but also increase the amount of IL-4 production from OT-II T-cells." (PMID 21966467, 2011). "The outcome of infection in leishmaniasis is mainly determined by the Th1 versus Th2 effector response and the generation of IL-12 and IL-10 by the infected macrophages is important for this decision." (PMID 21935379, 2011). "Previous work from our laboratory has shown that Ara-LAM is involved in IL-12 induction and IL-10 attenuation during infection demonstrating the suitability of it as a potential candidate for immunotherapy to cure VL." (PMID 21935379, 2011).
infection (continued). "In a study it was observed that after the infection of microglial cells by M. tuberculosis, the production of cytokines IL-1A and IL-10 was prevented." (PMID 22151930, 2011). "Conversely, lactoferrin decreased IFN-γ and increased IL-10 in an infection model of Toxoplasma gondii, suggesting a promotion of a TH2 response." (PMID 22567270, 2011). "Protection against lethal GBS infection through rGAPDH maternal vaccination was due to neutralization of IL-10 production soon after infection." (PMID 22114550, 2011). "Possibly, infants with higher IL-10 levels in NPA during acute RSV infection continue to have high levels of IL-10 during subsequent infections and develop more PBW." (PMID 21910858, 2011). "Thesupernatants from 4x infected mice were particularly rich in Th2-type cytokines, andover the first 4 days after infection contained 3- to 5-fold increased levels of IL-4and IL-13 compared to 1x mice, as well as significantly greater quantities of IL-10." (PMID 21445234, 2011). "Altogether, these results strongly suggest that the elevated IL-10 serum levels detected upon infection were due to GBS GAPDH." (PMID 22114550, 2011). "Accordingly, in vitro infection of human macrophage with T. gondii resulted in an increased expression of IL-10 from these cells, which inversely correlated with iNOS expression and NO generation." (PMID 21526166, 2011). "In this study, we observed the production of both pro (IFN-γ) and anti-inflammatory (IL-10) cytokines during infection, but IL-10 production increased when the parasite density was elevated." (PMID 21917128, 2011). "While many aspects of the chicken embryo response resembled murine infections, we also observed significant differences: In contrast to systemic infections in mice, IL-10 had a beneficial effect in chicken embryos." (PMID 21603634, 2011). "TNF-alpha, IL-6 and IL-10 expression was also modulated upon infection showing a TLR2-specific dependent IL-10 secretion." (PMID 20523725, 2010). "Transcript levels for various cytokines/chemokines (KC [CXCL1], MCP-1 [CCL2], MIP-1α, IFN-γ, IL-4, IL-5, IL-6 and IL-10) were determined in lungs of infected mice on days 1, 6 and 9 post-infection." (PMID 20661429, 2010). "Dengue virus-infected peripheral blood leukocytes produced mainly TH1 cytokines early after infection, but then shifted to producing IL-10 late after infection." (PMID 20661470, 2010). "Compared to WT Mtb, infection of primary macrophages with Tn:Rv0431 resulted in secretion of much larger amounts of IL-10, IL-6, MCP-1, IL-12p40 and TNFα as judged by ELISA and higher levels of transcripts for GM-CSF and COX-2 as measured by qRT-PCR." (PMID 21170273, 2010). "In fact, when we compared experimental lagochilascariosis in C57BL/6 and BALB/c mice, the latter were more resistant to infection and produced more IFNγ and IL-10." (PMID 20721343, 2010). "The metacestode most likely achieves the late infection stage Th2 expansion through the induction of regulatory cytokines, such as IL-10 and TGF-β." (PMID 20368974, 2010). "An increase in the numbers of CD4+ T cells was observed in the lungs and dLN of IL-10−/− mice at day 29 after infection with Mtb as compared with controls." (PMID 20518032, 2010). "IL-10 levels subsequently decreased in all of the isolates except two, in which production increased until infection resolved." (PMID 20500810, 2010). "Recent studies have shown that Th1 cell themselves can produce IL-10, which is essential for the inhibition of exaggerated Th1 cell responses during infection." (PMID 20072623, 2010). "This analysis showed that infection status was significantly associated with PCA1 (schistosome-specific antibody responses), PCA 3 (IL-10, anti-worm IgA, IgE and anti-egg IgG1) and PCA 5 (INF-γ and IL-2)." (PMID 21039611, 2010). "This cytokine is usually considered as immunoregulatory or immunosuppressive depending on the context, but research has identified profound effects of IL-10 expression early in infection." (PMID 20661470, 2010).
infection (continued). "At the cytokine level, the high IL-10 in the lungs during the initial 2 months of infection, was fundamental to delay clearance in the lower respiratory tract and probably contributed to the persistence of bacteria in the nasal cavity and associated shedding." (PMID 20738862, 2010). "Spleen cells from males produced higher levels of IL-10 than those from females, resulting in a relation of two- and threefold at days 7 and 30 after infection, respectively." (PMID 20505765, 2010). "Accordingly, with the progress of infection, the levels of il4 increased quickly, especially at w 6 post-infection when a large number of eggs appeared, and il10 expression showed a slight elevation." (PMID 23554641, 2010). "Conversely, infection of RLEC-CM DCs induced a statistically significant up-regulation of IL-10 secretion (p<0.01)." (PMID 20544029, 2010). "We provide evidence that IL-10−/− mice show enhanced control of Mtb infection with significantly reduced bacterial load in lungs and spleen, which was maintained over the course of infection studied." (PMID 20518032, 2010). "Determination of serum cytokine levels at various times post-infection revealed that control animals produced an initial burst of IL-10, which peaked at 12 h, and then declined to basal levels by 48 h." (PMID 21124939, 2010). "RAG° mice receiving chronically stimulated T cells also had higher levels of TNFα, IFN-γ and IL-10, in plasma at day 7 of infection, than those receiving rested T cells." (PMID 21124875, 2010). "Then, it is possible that IL-10 and/or IFNγ, which increase during infection, as well as TLR ligands expressed by T. cruzi or parasite antigens trigger BAFF secretion." (PMID 20454564, 2010). "In C57Bl/6 mice, an early significant IFN-γ response was evident along with increased IL-6 and IL-10, which then decreased to near control levels by day 15 post-infection." (PMID 20625554, 2010). "Genotypic frequencies and associations of SNPs in IL10, IL10RA/B, TGFB1, and SLC11A1 with MAP-infection status." (PMID 20398313, 2010). "Taken together, these results suggest an imbalance between the inflammatory (increased release of IL-6) and anti-inflammatory (increased release of IL-10) responses in acute phase of infection in aged patients." (PMID 20716329, 2010). "After H strain infection, the expression levels of IL-4, IL-13 and IL-10 in the bursa of chickens were up-regulated and peaked at 3 dpi and then declined at 5 dpi." (PMID 21143846, 2010). "In unimmunized mice, co-inhibition of TGF-β and IL-10 early in infection, or depletion of Treg, restores proinflammatory responses and parasite clearance." (PMID 20502667, 2010). "In these mice, IL-10 levels progressively rose during the initial stages of infection and peaked at 72 h at which time the bacteria were completely cleared from the circulation." (PMID 21124939, 2010). "To explore a potential role of IL-10 in the control of the immune response to Mtb H37Rv, we first investigated the expression of this cytokine in the lungs of mice upon aerogenic infection." (PMID 20518032, 2010). "Labeling of frozen sections of LGT with anti-IL-10 also confirmed the presence of CD11c+ cells producing this cytokine on day 24 following infection." (PMID 21079691, 2010). "Following a genital tract primary infection, nu/nu mice responded with IL-10 mRNA expression levels in the LGT of comparable magnitude irrespective of if the CD4+ T cells were IL-10-deficient or normal." (PMID 21079691, 2010). "More recently, increase CXCL10 and IL-10 expression were observed upon infection of human monocytes with L. braziliensis." (PMID 20559550, 2010). "The similarity in the transcriptional signatures resulting from L. mexicana infection and IL-10 stimulation is consistent with studies showing that Leishmania induces IL-10 during infection and that IL-10 plays an essential role in Leishmania pathogenesis." (PMID 20361029, 2010).
infection (continued). "With respect to schistosomosis, most of the chronic patients presented a Th2 profile with low production of gamma interferon (IFN-γ) as compared to subjects resistant to this infection, while the intensity of infection favors the production of IL-10." (PMID 22043257, 2010). "Pathways activated by IMI were IL-10 Signaling and IL-6 Signaling which likely reflected counter mechanisms of mammary tissue to respond to infection." (PMID 19925655, 2009). "Infection of cells with T. gondii resulted in suppressed IL-10 mRNA induction following LPS + IC stimulation." (PMID 19859561, 2009). "Naive mice challenged with pRBCs or sporozoites showed a similar induction of IFN-γ, TNF-α, and IL-10 in the serum by 120 hr post blood-stage infection." (PMID 19154991, 2009). "Infection with either organism also stimulated production of IL-10 and IL-12p70 (P < 0.05, paired-samples t-test) in the MoDC cultures." (PMID 19397822, 2009). "The decreased pro-inflammatory cytokines and increased IL-10 observed here would be expected to decrease resistance to infection, and we have previously reported such a decrease in mice treated by acute administration of ethanol." (PMID 19765273, 2009). "Our study suggested that circulatory cytokines, namely, IL-4, IL-8, and adhesive molecules like ICAM-1 were enhanced after infection with C. pneumoniae whereas in contrast to this IL-10 and IFN-λwere lowered." (PMID 19360108, 2009). "In general, single FIVC infection elicits an overall increase in IL10, IL4, and IL12, but lower expression of CD25, and CD8 throughout the first 31 days of infection (day 31–59 of the experiment) compared to other groups." (PMID 19806226, 2009). "Four hours post infection, serum IL-10 was detectable in mice immunized with LLO-Lm-OVA, either alone or in combination with ActA-Lm-OVA, and required the adapter protein MyD88." (PMID 19730694, 2009). "IL10 mRNA peaked during acute infection at 4 days p.i. and then declined to uninfected levels by 7–14 days p.i.." (PMID 20019816, 2009). "There were weak but significant correlations between the five markers of infection and the pro- and anti-inflammatory cytokines, interleukin-6 (IL-6), interleukin-8 (IL-8), interleukin-1Ra (IL-1Ra) and interleukin-10 (IL-10)." (PMID 19675669, 2009). "In piglets infected with virulent PRRSV, IL-10 levels were significantly increased in serum at 8-14 days of infection (p < 0.05)." (PMID 19860914, 2009). "Similar to intraperitoneal inoculation, IL-10−/− mice also had increased survival after footpad infection." (PMID 19816558, 2009). "Macrophages harvested from TLR1−/− and TLR6−/− mice expressed TNF, IL-6, MCP-1, and IL-10 in response to LVS infection in vitro at comparable or higher levels than B6 mice." (PMID 19936231, 2009). "The values of serum IL-10 in the L. casei group were higher than in the control group on d 3 and 5 post-infection." (PMID 19835595, 2009). "In contrast, it has been suggested that increased IL-10 following CB3 infection in human monocytes leads to a dysregulation of the immune response to the virus and ultimately allows for the progression to the chronic disease." (PMID 19587788, 2009). "FIVC single infections separate from uninfected cats and single PLV infections due to higher levels of IL10 and lower CD4 counts." (PMID 19806226, 2009). "Whereas a significant increase of IL-10 mRNA expression was observed after 4 weeks infection in the corpus of WT-infected as well as in antrum and corpus of mutant-infected gerbils." (PMID 19270747, 2009). "In the L. casei group, IL-10 in BAL was significantly higher than in the control group since d 2 post-infection." (PMID 19835595, 2009). "IL-10 concentrations higher than 5 pg/ml were detected in 10 of the 44 plasma samples tested at pre-infection in German Landrace." (PMID 19383119, 2009). "Epstein-Barr virus (EBV) takes advantage of the immunomodulatory effects of IL-10 by expressing a viral homolog of IL-10 during infections." (PMID 19816558, 2009).
infection (continued). "Mice treated with vancomycin but not colonized with VRE had modestly but statistically significantly higher plasma TNF-α and IL-10 levels 6 hours after the start of the infection." (PMID 19710930, 2009). "In case of Polytope DNA vaccines, though IL-10 increasedafter challenge infection but these levels were significantly low as compared tocontrol group." (PMID 19956549, 2009). "ELISA results showed that IL-12/23 p40 and TNF-α production in plasma from IL-10−/− mice was higher than wild-type mice plasma samples on day 2 after infection." (PMID 19816558, 2009). "We observed that IL-10 expression was up-regulated 4- fold at 5 h and 90-fold at 24 h post-infection (p.i.), while expression of IL-4, IL-13 and another immunosuppressive cytokine, TGF-β, were not significantly altered at both time points (data not shown)." (PMID 19816558, 2009). "There was no indication from the ELISA results that antibody responses were protective in C57BL/6 IL-10-/- mice against infection with any of the tested strains of C. jejuni used for challenge." (PMID 19296832, 2009). "At day 7 post-infection there was a 4-fold increase in IL-10 gene expression in response to both strains." (PMID 19759900, 2009). "By day 4, however, there was a 9-fold increase in IL-10 gene expression in response to WT infection, whereas IL-10 gene expression in response to ΔPT infection remained near control levels." (PMID 19759900, 2009). "Results showed that IL-10 production began to increase in plasma as early as 6 h p.i. and reached approximately 18-fold at day 5 (120 h) compared to baseline (before infection, 0 h)." (PMID 19816558, 2009). "On day 5 post-infection, IL-10+ CD4+ T cells showed very variable expression of CD25 with approx. 60% being CD25−, indicating that they are not a typical nTreg population." (PMID 18401464, 2008). "Studies by Lyons and colleagues indicated that increased IL-10 production correlates with subsequent septic events, and in the burn mouse IL-10 appears to induce decreased resistance to infection." (PMID 18564432, 2008). "In contrast to the other cytokines, IL-10 mRNA levels increased to a similar extent in both groups at all time points post-infection." (PMID 18369473, 2008). "Together, these data show that in the spleen regardless of vaccination functional Tlr4 results in a higher IL-10 response after infection." (PMID 18498620, 2008). "Because dermal macrophages stain for IL-10 in situ, we generated dermal-type macrophages from monocytes in the presence of IL-10 to study their infection by dengue virus." (PMID 18827881, 2008). "In both infections, from day 5 onwards, the vast majority of the IL-10+ cells were CD4+ lymphocytes." (PMID 18401464, 2008). "Here we show that a unique MHV68 latency-associated gene product, the M2 protein, is required for the elevated serum IL-10 levels observed at 2 weeks post-infection." (PMID 18389062, 2008). "Transcription of il6, tnf, il10, mip2, and kc was strongly upregulated upon infection in the presence of XIAP, while induction of ifnb, il1b, ido, and inos was not significantly altered." (PMID 18769721, 2008). "We find that CD4+ T cells are a significant source of IL-10 by day 5 of both PyL and PyNL infections, since IL-10 mRNA is significantly upregulated in splenic CD4+ cells on days 5 and 7 post-infection compared with cells from uninfected mice." (PMID 18401464, 2008). "MLN cells (MLNC) from H. polygyrus mice respond briskly to parasite antigen challenge in vitro with IL-10 release over the course of infection." (PMID 17563918, 2007). "Logistic regression analyses showed that infection status was significantly affected by PCA 2 (made up largely of IL-10) (p = 0.039, β = 0.51 with a SE of 0.247, -2 Log likelihood of 6.522) and that the effect was positive." (PMID 18045464, 2007). "We chose mice that were persistently infected with LCMVClone13 (day 30 p.i.)and injected them with normal rat IgG or anti-IL-10 antibodies on days 30, 32 and 34 post-infection." (PMID 17570849, 2007).